Y_RNA (Y RNA )
Gene: Miscellaneous RNA gene on chromosome 15 (45,047,103 to 45,047,215, reverse strand). Ensembl gene ENSG00000252171.
Homologues: Orthologues: chimpanzee Y_RNA (100% identical), macaque Y_RNA (88% identical). Paralogues in human: Y_RNA (88% identical), Y_RNA (86% identical), Y_RNA (85% identical), Y_RNA (84% identical), RNY1P5 (83% identical), Y_RNA (83% identical), Y_RNA (82% identical), RNY1P6 (81% identical), Y_RNA (81% identical), Y_RNA (80% identical), Y_RNA (79% identical), RNY1P1 (78% identical), and 96 more.